CXCR3 (C-X-C motif chemokine receptor 3)
Diseases named in the same sentence as CXCR3 in open-access papers (continued):
Sharing a sentence is not in itself a finding about the gene and the disease.
breast carcinoma (continued). "To understand the clinical relevance of our mouse studies, we investigated the possible correlation between CXCR3 expression with human breast cancer progression." (PMID 26485767, 2015). "The CXCR3 expression level was clearly higher in the basal cancer types than in the luminal types in 10 human breast cancer cell lines examined using flow cytometry analysis." (PMID 26485767, 2015). "AMG487 is a specific small molecular inhibitor of CXCR3, and it has significant inhibitory effect on tumor progression including breast cancer, colon cancer, and osteosarcoma." (PMID 26485767, 2015). "For the host compartment, deletion of CXCR3 in all host cells in 4T1 mammary tumor model significantly decreased metastasis." (PMID 26485767, 2015). "For example, inhibition of CXCR3 signaling by either gene silencing or small molecule inhibitors decreased the number of pulmonary metastases formed by breast cancer cells." (PMID 25415223, 2014). "In summary, our results provide a mechanistic link between the COX pathway and a reduced infiltration of tumor-suppressive lymphocytes in breast cancer through the modulation of intratumoral CXCR3 chemokine release." (PMID 22333315, 2012). "Additionally, it has previously been described that HER2- ER+/− breast cancer patients had an increased frequency of Th2/ Th17 cells, based on the surface marker expression of CXCR3, CCR4, and CCR667." (PMID 39843922, 2025). "Moreover, it is interesting that AE training can also promote tumor immune control by enhancing the infiltration of CD8+ T cells via the CXCR3 signaling pathway, hence rendering breast cancer more sensitive to immune checkpoint inhibition therapy." (PMID 41480347, 2025). "In contrast, the amount of CD8 and CXCR3 in breast cancer patients may be correlated with immunotherapy efficacy and predict better clinical outcomes." (PMID 38263419, 2024). "Ccl17 and Cxcr3 increased in mammary tumors that protects cancer cell survival and induce tumor growth to promote breast cancer lung metastasis Hypoxia-induced chemokine Sema3a stimulates tumor-associated macrophages to the alternative type (M2), leading to pro-tumor immunity." (PMID 35768767, 2022). "In addition, SRC-3 inhibition by SI-2 and SRC-3 KD increased C-X-C motif chemokine ligand 9 (Cxcl9) expression in breast cancer to recruit C-X-C motif chemokine receptor 3 (Cxcr3)-expressing cytotoxic immune cells into breast tumors." (PMID 36316775, 2022). "Whether genetic or pharmacological approaches inhibit CXCR3, its ability to affect breast cancer metastasis depends on the presence of normal NK cells." (PMID 36479091, 2022). "Notably, IP-10 was shown to trigger the emergence of dormant breast cancer cells, making IP-10/CXCR3 as a potential target for breast cancer therapy." (PMID 34572567, 2021). "In addition, in a mouse model, a small molecule CXCR3 antagonist blocked lung metastasis of breast cancer." (PMID 34345201, 2021). "Goldberg-Bittman reported that CXCR3 was overexpressed in breast cancer." (PMID 34345201, 2021). "Importantly, CXCR3 was also expressed in subsets (range 3.8–11.1%) of cancer cells isolated with high purity from pleural effusions or ascites of four breast cancer patients." (PMID 32198421, 2020). "Moreover, targeting CXCR3 was proposed as a strategy to prevent metastatic formation in breast cancer through the inhibition of CXCR3-dependent cancer cell migration and the enhancement of host antitumor immunity." (PMID 32225066, 2020). "Moreover, we demonstrate that a subset of breast cancer cells with high metastatic potential expresses the cell surface receptor CXCR3, which binds CXCL9/10." (PMID 32198421, 2020). "Ultimately, interruption of the CXCL9/10-CXCR3-mediated paracrine loop through systemic inhibition of JNK or CXCR3 represents a potential future strategy to inhibit metastatic colonization of the lungs in basal-like breast cancer." (PMID 32198421, 2020).
breast carcinoma (continued). "Collectively, our data suggest that systemic antagonism of CXCR3 may be an effective strategy to disrupt cancer cell-fibroblast crosstalk in the lungs in basal-like breast cancers." (PMID 32198421, 2020). "Finally, to address the putative link between CXCR3+ cancer cells and clinical prognosis, we clustered tumor samples from breast cancer patients according to the expression of CXCR3+ cell signature (CXCR3S)." (PMID 32198421, 2020). "Importantly, we detect CXCR3+ subsets of cancer cells in primary cultures of pleural effusion and ascites samples from patients with metastatic breast cancer, indicating relevance of this molecular interaction in human metastasis." (PMID 32198421, 2020). "In addition to the CCL5–CCR5 axis, hypoxia induces HIF-dependent CXCL10 secretion from MSC, which recruits CXCR3+ breast cancer cells and promotes lung metastasis through the CCL10–CXCR3 axis." (PMID 27136535, 2016). "Moreover, in a murine model, antagonism of CXCR3 by a small molecule inhibitor blocked pulmonary metastasis of breast cancers." (PMID 27297979, 2016). "Notably, systemic administration of a small molecular inhibitor of CXCR3 (AMG487) inhibited lung metastasis of CRC as well as breast cancer in murine models." (PMID 27136535, 2016). "Importantly, CXCR3 expression in clinical breast cancer samples correlated with progression and metastasis." (PMID 26485767, 2015). "Interestingly, we observed a correlation of CXCR3 level with TβRII expression in myeloid cells that we previously reported play a critical role in breast cancer metastasis and host immune suppression." (PMID 26485767, 2015). "Both CXCL10 and its receptor CXCR3 are on the other hand over-expressed in many tumours and have been connected to poor prognosis and metastasis in a number of cancers, including colon cancer, multiple myeloma, breast cancer and basal cell carcinoma." (PMID 24395654, 2014). "Still, origin and regulation of CXCR3 chemokines in human breast cancer are poorly understood." (PMID 22333315, 2012). "As endothelial cells seem to produce CXCR3 chemokines in response to similiar stimuli as cancer cells they might also participate in modulating immune infiltration in breast cancer." (PMID 22333315, 2012). "Elevated expression of CXCR3 in human mammary carcinoma correlates with poor survival." (PMID 20419088, 2010). "Therefore, CXCR3 not only participates in the initiation and progression of breast cancer but may also regulate tumor metastasis and prognosis by influencing the tumor immune microenvironment." (PMID 40786052, 2025). "However, it should be noted that contradictory results are also reported with regard to CXCR3 expression and survival of human breast cancer patients likely due to the reported expression of CXCR3 on breast cancer cells which can promote CXCL9/10-mediated motility." (PMID 37055433, 2023). "In addition, CAFs provide CXCL9 and CXCL10 to contribute to the CSC phenotype and proliferation of metastatic breast cancer cells, which bind to CXCR3 and activate JNK-IL-1 signaling in breast cancer cells; thus, a positive loop is established and MAFs are further activated." (PMID 34112258, 2021). "Growing evidence suggests that CXCR3 may play an important role during breast cancer progression." (PMID 32198421, 2020). "Thus, JNK activity and CXCR3 expression may mark a unique population of breast cancer cells that strategically communicate with stromal fibroblasts to establish a supportive metastatic niche tailored to their phenotype." (PMID 32198421, 2020). "Also, the CXCR3 expression on breast cancer cells is involved in promoting bone metastasis." (PMID 30177620, 2018). "Importantly, CXCR3 expression correlates with human breast cancer progression and metastasis." (PMID 26485767, 2015). "Furthermore, CXCR3 was differentially expressed in ER- and ER + breast cancer patients (GSE22220)." (PMID 26485767, 2015).
breast carcinoma (continued). "Similarly, under hypoxia, MSCs promote breast cancer metastasis through CXCR3/CXCL10 interaction." (PMID 25110692, 2014). "The CXCL-9,-10,-11/CXCR3 axis, dependent on IFN-γ signaling activity, was overexpressed in primary breast cancer samples of patients who developed brain metastasis." (PMID 39262976, 2024). "This suggests that neurons in the TME of breast cancer are able to promote tumor cell migration by releasing CXCL10 or CXCL12 and combining with CXCR3." (PMID 39429695, 2024). "In our previous study of transcriptome analysis of mammary tumors of PyMTSB2−/− mice, the expression levels of cancer immune modulated genes (ANXA3, CCL17, CXCL13, CXCR3, IFN-γ, NR4A1, and SEMA3a) were significantly changed." (PMID 38956496, 2024). "Zhu and colleagues showed, in a murine breast cancer model, that CXCR3 acts both on the tumor and host compartments by promoting metastasis and impairing the host’s anti-tumor immunity, and that both could be improved through chemical and genetic approaches to CXCR3 inhibition." (PMID 37686653, 2023). "A minor molecular weight antagonist of CXCR3, AMG487, was found to inhibit tumor metastasis in a mouse breast cancer model." (PMID 36479091, 2022). "The 4T1 family of isogenic mammary tumors has been used by several researchers to identify important genes that drive breast cancer metastasis such as TWIST1, FOXC2, and CXCR3 39-41." (PMID 35910801, 2022). "Gene of Ccl17, Cxcl13, Cxcr3, IFN-γ, and Sema3a, were significantly decreased while the Anxa3 and Nr4a1 were significantly upregulated in SB2−/−;PyMT mammary tumors." (PMID 35768767, 2022). "Given the importance of A3SS in CXCR3, genome-wide analysis of A3SS events was performed to identify events that were differentially spliced between breast cancer tissue and adjacent normal tissue." (PMID 34440489, 2021). "We observed a significantly higher expression of both CXCR3 and CCR2 in canine mammary tumors that gave local or distant metastases." (PMID 32225066, 2020). "Our own studies indicate that the deletion of PTPN2 in CAR T cells drives the expression of CXCR3 and the trafficking of CAR T cells to CXCL9/10‐expressing mammary tumours." (PMID 31803974, 2020). "The CX3CR1/CX3CL1 and CXCR3/CXCL10 axes have been demonstrated to be involved in the proliferation, survival, and metastasis of various malignant tumor types, including breast cancer, and were suggested to predict the site of metastatic relapse." (PMID 31026363, 2019). "It has been reported that both CXCR3 and its ligand CXCL10 are highly upregulated in breast cancer cells." (PMID 30177620, 2018). "CXCR3 and CXCL13 expression were also included because they have been shown to correlate with breast cancer prognosis." (PMID 25505134, 2015). "In hypoxic environments, breast cancer cells express high levels of HIF-1, which promotes the expression of CXC chemokine receptor 3 (CXCR3) and CXC chemokine receptor 5 (CXCR5) on breast cancer cell lines." (PMID 24502410, 2014). "Furthermore, subsets of CD8 + T cells displayed expression of CCR2 and CCR4, albeit to a lower extent than CXCR3, in human CRC, pancreatic neuroendocrine and breast cancers." (PMID 40595293, 2025). "A previous study in a breast cancer mouse model, using a surrogate molecule, showed that HER2-TDB leads to increased numbers of CXCR3+ CD3+ murine T cells within the tumor, suggesting that this mechanism might be shared among different T cell engagers." (PMID 33406104, 2021). "In breast cancer, NK cells take advantage of their own production of IFN-γ to enhance the secretion of chemokines CXCL9, CXCL10, and CXCL11 by tumor cells, which in turn accelerate the infiltration of CXCR3 expressing NK cells into the tumor site." (PMID 25110692, 2014).
breast carcinoma (continued). "Notably, we find that the chemokine receptor CXCR3, that binds CXCL9/10, is specifically expressed in a small subset of breast cancer cells, which exhibits tumor-initiating ability when co-transplanted with fibroblasts and has high JNK signaling that drives IL-1α/β expression." (PMID 32198421, 2020). "In MDA-MB-435 and MCF-7 breast cancer cells, CXCR3 and CXCL10 are upregulated via the Ras signaling pathway, which contributes to breast cancer development, suggesting that CXCL10-CXCR3 autocrine function may play an essential role in breast cancer motility and metastasis." (PMID 30177620, 2018). "Consequently, exercise may have a direct effect on breast cancer cell growth via the CXCR3 axis, although this was not explicitly demonstrated in our study." (PMID 40362215, 2025). "In addition, there are other GPCRs and ligands that may recruit Tregs, such as CCR5/CCL5 in colorectal cancer (CRC) and pancreatic cancer, CCR6/CCL20 in HCC and breast cancer, and CCR10/CCL28 in ovarian cancer, while CXCR3 and CXCR6 are expressed by Tregs infiltrating renal cell carcinoma." (PMID 25110692, 2014). "We chose genes that encode proteins that regulate T cell activation or differentiation, such as PD-L2, Gal9, CD86, CXCR3, CCR2, which have not yet been investigated in canine mammary cancers." (PMID 32225066, 2020). "For interaction studies, we chose MCF-7 breast cancer cells, since they highly express CXCR4 and CXCR7 at the protein level but not CXCR3 (another target for CXCL11)." (PMID 24770893, 2014). "Since breast cancer cells are an important target, we examined the expression of CXCR4 and CXCR7 in various cell lines and selected MCF-7 cancer cells as a representative that expresses both receptors at comparable levels but not CXCR3." (PMID 24770893, 2014).
COVID-19 (92 papers, 2020 to 2025). A disease caused by infection with severe acute respiratory syndrome coronavirus 2. "This study confirmed that CXCL9, CXCL10, CXCL11, and CXCR3 levels are associated with disease severity in patients with COVID-19." (PMID 37493737, 2023). "This study emphasizes the association between CXCL9, CXCL10, CXCL11, and CXCR3 levels and disease severity in patients with COVID-19." (PMID 37493737, 2023). "When compared to healthy controls, a trend towards a loss of CXCR3+ in COVID-19 and loss of CXCR3+ and CXCR6+ NK cells in influenza patients was observed." (PMID 35371005, 2022). "Upregulation of CXCL10, the ligand of CXCR3, is associated with COVID-19 severity promoting chemoattraction via CXCR3 for activated lymphocytes and monocytes." (PMID 36238301, 2022). "Th1 cells observed in individuals with COVID-19 demonstrated a distinctive expression of CXCR3 and CCR6, in addition to transcripts encoding cytokines and chemokines with anti-viral properties, such as CD154, IFN-γ, IL-2 (interleukin-2), and TNF (tumor necrosis factor)." (PMID 38675727, 2024). "Loss of CXCR3 in COVID-19 patients was observed in all memory T cell subsets." (PMID 35371005, 2022). "So, it has been suggested that the chemokine CXCL10, through CXCR3, is associated with inflammatory diseases and may be involved in the development of COVID-19." (PMID 35409036, 2022). "It remains to be seen whether the inhibition of CXCL10 production from epithelial cells could have a therapeutic potential in selected COVID-19 patients at increased risk of severe disease, by limiting the infiltration of CXCR3+ immune cells into lung tissue." (PMID 33284849, 2020). "Speculation of the underlying mechanism of CXCR3 in COVID-19 has mainly come from animal models." (PMID 34471088, 2021). "Here, the proportion of CD14+ monocyte cells and the expression level of CXCR3 of Tregs in severe COVID-19 patients supported that the ligand-receptor pair of PF4_CXCR3 promotes the activation of HLA_DR+ Tregs in severe COVID-19 patients." (PMID 40114921, 2025). "CXCL9, CXCL10, CXCL11, and CXCR3 levels were significantly higher in patients with severe COVID-19 group than in those with moderate disease." (PMID 37493737, 2023). "We found that spike-specific CXCR3+ TFH cells were associated with antibody response magnitude and were more responsive than spike-specific CXCR3− TFH cells upon antigen stimulation in both COVID-19 convalescents and vaccinees." (PMID 37802996, 2023). "The primary aim of this study was to investigate the association between mortality and the CXCL9, CXCL10, CXCL11, and CXCR3, chemokine levels, which contribute to the pathogenesis of COVID-19 through hyperinflammation, in patients with COVID-19." (PMID 37493737, 2023). "We did not observe higher spike-specific IgG production in CXCR3+ TFH cells compared with CXCR3− TFH cells from COVID-19 convalescents and vaccinees cocultured with autologous memory B cells, as expected." (PMID 37802996, 2023). "An increase in the blood levels of Th2 cells with the CXCR3− CCR6− phenotype was closely associated with the severe course of the disease and poor outcomes in patients with severe COVID-19." (PMID 36674665, 2023). "The levels of CXCL9, CXCL10, CXCL11, and CXCR3 were significantly higher in patients with COVID-19 than in healthy controls." (PMID 37493737, 2023). "In this study, we demonstrated that spike-specific CXCR3+ TFH cells are more persistent than spike-specific CXCR3− TFH cells in COVID-19 convalescents." (PMID 37802996, 2023). "Immunophenotyping results of PBMC demonstrated that specific subsets of CXCR3+ monocytes were increased in COVID-19 convalescents, but total monocytes were comparable between groups." (PMID 38259488, 2023). "In the ROC curve analysis of the ability of CXCL9, CXCL10, CXCL11, and CXCR3 to discriminate between moderate and severe COVID-19, the AUC values were 0.702, 0.939, 0.933, and 0.857, respectively." (PMID 37493737, 2023).